IDH2 (isocitrate dehydrogenase (NADP(+)) 2)
Diseases named in the same sentence as IDH2 in open-access papers (continued):
Sharing a sentence is not in itself a finding about the gene and the disease.
glioblastoma (170 papers, 2011 to 2025). The most malignant astrocytic tumor (WHO grade IV). "On the other hand, glioblastomas with IDH1/IDH2 mutations are defined as “secondary” glioblastomas, which arise from low-grade diffuse gliomas, while IDH-wild-type is considered “primary” or “de novo” glioblastoma." (PMID 40002465, 2025). "Mutations in IDH1/IDH2 (abbreviated IDH) were found in 10–12% of brain tumors that were histologically classified as glioblastoma." (PMID 40564017, 2025). "Mutations in isocitrate dehydrogenase 1 (IDH1) and isocitrate dehydrogenase 2 (IDH2) are associated with improved survival rates among patients with glioblastoma and are positive prognostic predictors of overall survival." (PMID 38173841, 2023). "PI3K, EGFR, IDH1 and IDH2 mutations are examples of factors that alter the glioblastoma epigenome to confer increased growth and resistance to therapy." (PMID 34769339, 2021). "Mutations in isocitrate dehydrogenase genes IDH1 and IDH2 are frequently found in diffuse and anaplastic astrocytic and oligodendroglial tumours as well as in secondary glioblastomas." (PMID 32382048, 2020). "For example, the isocitrate dehydrogenase (IDH) gene mutations (IDH1 and IDH2) are detected in more than 70% of sporadic low-grade gliomas and in the majority of glioblastomas arising from lower grade gliomas." (PMID 31906320, 2020). "Both results confirmed differential in vivo growth of glioblastoma cells harboring contrasting IDH2 mutations." (PMID 31105869, 2019). "Mutations in IDH genes (IDH1 and IDH2) have been revealed in the majority of lower-grade gliomas and in secondary glioblastoma multiforme, and predict better survival." (PMID 31444316, 2019). "Mutations in either IDH1 or IDH2, commonly seen in glioblastomas, contribute to downregulation of BCAT1 through DNA methylation of the BCAT1 promoter and the corresponding epigenetic silencing of BCAT1." (PMID 29211698, 2018). "Exons 4 of IDH1 and IDH2 genes were screened in all cases of glioblastoma targeting possible mutations." (PMID 28785587, 2017). "IDH1 mutations occur at high frequency in WHO grade II and III astrocytoma (>80% of cases), precursor lesions of secondary glioblastoma, whereas IDH2 mutations occur largely in oligodendroglial tumors, with much lower frequency." (PMID 25785247, 2015). "Several previous studies have demonstrated the important role of IDH1/IDH2 mutations for determining the prognosis of glioblastoma patients." (PMID 24868540, 2014). "The genes for IDH1 and IDH2 carry specific mutations in 70%–80% of low-grade gliomas, in approximately 50% of anaplastic gliomas, and in more than 5% of glioblastomas." (PMID 24511544, 2014). "Glioblastoma samples with confirmed mutations of the IDH1 or IDH2 gene was used as positive controls." (PMID 24386123, 2013). "Recent mutational analyses also revealed that somatic mutations in the NADP-dependent isocitrate dehydrogenase genes, IDH1 and IDH2, were associated with an increased overall survival of glioblastoma patients." (PMID 21752281, 2011). "Furthermore, IDH mutations, such as the ones associated with IDH1 and IDH2, have a profound impact on glioblastomas." (PMID 39329757, 2024). "IDH1 and IDH2 mutations were first found in adult glioblastoma multiforme (GBM) patients." (PMID 35765075, 2022). "In addition, IDH2 mutations are also more frequent in secondary glioblastomas than in primary glioblastomas." (PMID 36678688, 2022). "Indeed, there is a phase 1–2 trials to test metformin in glioblastoma-solid tumor patients with IDH1 or IDH2 mutated." (PMID 35008275, 2021). "We next interrogated whether mutations in IDH2 could affect the response to chemotherapeutic drugs widely used in the standard of care for glioblastoma." (PMID 31105869, 2019).
glioblastoma (continued). "As hypothesized, we found that IDH2 mutations greatly affected the growth of glioblastoma tumor cells both in vitro and in vivo." (PMID 31105869, 2019). "IDH1/IDH2 mutations are known to be diagnostic molecular markers of secondary glioblastoma." (PMID 26143636, 2015). "Somatic mutations in IDH1 and IDH2 are described in glioblastomas (GBMs)." (PMID 26948489, 2015). "The IDH1 and IDH2 genes are mutated in glioblastoma and AML cancer patients." (PMID 22174824, 2011). "Mutations of IDH1 (codon 132) or IDH2 (codon 172) allow discrimination between two classes of glioblastoma (GBM), IDH-wildtype and IDH-mutant, with differing genomic and epigenomic landscapes and prognoses." (PMID 28915660, 2017). "IDH2, an isoform of isocitrate dehydrogenase, plays a role in metabolic reprogramming and oncometabolite production in glioblastoma." (PMID 40282990, 2025). "ATRX, OLIG2, MGMT, and IDH2 were selected due to their critical roles in glioblastoma biology and prognosis." (PMID 40282990, 2025). "Key molecular players, such as ATRX, OLIG2, MGMT, and IDH2 proteins, contribute to critical oncogenic processes like chromatin remodelling, glioblastoma cell fate and de-differentiation, DNA repair and metabolic reprogramming." (PMID 40282990, 2025). "These tests analyze tumor DNA and RNA to identify key genetic alterations, such as mutations in the IDH1 and IDH2 genes, MGMT promoter methylation, and EGFR amplification, which are pivotal in glioblastoma classification and prognosis." (PMID 39338377, 2024). "We report our institutional case of a diffuse astrocytoma with progression to secondary glioblastoma and concurrent IDH1/IDH2 mutations." (PMID 37077830, 2023). "Point mutations in the IDH1 or IDH2 gene are correlated with a better overall survival and while they occur frequently in lower-grade astrocytomas (WHO grade II and III) and secondary glioblastomas, they are rare (< 10%) in primary glioblastomas." (PMID 35180887, 2022). "In profound hypoxia (0.5% O2), IDH2 carboxylates α-KG to citrate to support glioblastoma cell growth and viability." (PMID 36497259, 2022). "In one case, the primary tumor was diffuse astrocytoma with IDH2 mutant, and the secondary tumor was glioblastoma with IDH 1/2 wild-type." (PMID 35505351, 2022). "Mutations of anabolic signaling proteins phosphoinositide 3-kinase (PI3K), epidermal growth factor receptor (EGFR), and isocitrate dehydrogenase types 1 and 2 (IDH1, IDH2) have been widely detected in glioblastoma patient biopsy samples." (PMID 34769339, 2021). "Mutations in human cytosolic and mitochondrial NADP-IDH (IDH1 and IDH2, respectively) are frequently identified in a variety of human cancers, such as glioblastoma (GBM) and angioimmunoblastic T cell lymphoma (AITL)." (PMID 34291089, 2021). "IDH1 or IDH2 mutations have been shown to be present in about 80% of grade II and grade III LGG and previously designated “secondary glioblastomas” (HGG)." (PMID 34277415, 2021). "Among 14 patients with IDH1 or IDH2 mutations, the median OS was reported to be 31 months, as compared to 15 months in 115 patients with IDH1 wild-type primary glioblastoma tumors." (PMID 32987955, 2020). "IDH2 is present in only 2% of all diffuse gliomas and less than 1% in adult primary glioblastoma – the study population in this study, therefore including IDH2 would not likely impact the results." (PMID 31036078, 2019). "All lines were found to be wild type for IDH1and IDH2 so can be regarded as glioblastoma, IDH-wildtype." (PMID 30894629, 2019). "We proceeded to evaluate the biological significance of the three IDH2 somatic mutations by employing the human UM87G and U251 glioblastoma cell lines; both lines carry wild type (WT) IDH2." (PMID 31105869, 2019).
glioblastoma (continued). "Using whole-genome sequencing and mutational analysis, Parson and colleagues identified recurrent mutations in IDH1 and IDH2 at high frequencies in WHO grade II and III astrocytomas, oligodendrogliomas, oligoastrocytomas, as well as in glioblastomas." (PMID 31242696, 2019). "This fact allows using IDH1and IDH2 as markers for distinguishing betweenlow-grade diffuse astrocytomas and secondary glioblastomas from PAs and primaryglioblastomas." (PMID 31413876, 2019). "For instance, overexpression or amplification of EGFR, mutations in IDH1 and IDH2 and phosphatase and tensin homologue (PTEN) mutations contribute to the pathogenesis of glioblastoma." (PMID 30382873, 2018). "Others have described a crucial role of the presence of active IDH2 for proliferation and survival of glioblastoma cancer cells in hypoxia." (PMID 29888201, 2018). "Recurrent mutations in IDH1 were identified in 2008 during an integrated genomic analysis of a set of human glioblastoma tumor samples, and subsequently IDH2 was identified in 2009 in a set of glioma tumor samples." (PMID 29882807, 2018). "Herein, we show that WEE1 deposits the pY37-H2B marks within the tumor suppressor gene, isocitrate dehydrogenase 2 (IDH2), to repress transcription in multiple cancer cells, including glioblastoma multiforme (GBMs), melanoma and prostate cancer." (PMID 29290954, 2017). "Further, increased WEE1 expression in glioblastomas and melanomas positively correlated with decreased IDH2 expression levels." (PMID 29290954, 2017). "Recent studies have pointed out the causal role of IDH1 mutations in Glioblastoma-CIMP and tight associations between IDH2 and TET2 mutations with other CIMPs (leukemia, enchondroma, and spindle cell hemangioma)." (PMID 26463173, 2015). "These heterozygous point mutations occur commonly at arginine residues, at codon 132 of IDH1 and at codon 172 of IDH2, and are definitive markers of secondary glioblastoma and a significantly improved prognosis." (PMID 25785247, 2015). "Furthermore, interest in human IDH1 and IDH2 in tumor metabolism studies has recently increased since the publication of a cancer genome project showing that the genes encoding IDH1and IDH2 were mutated in glioblastoma multiforme (GBM), in 2008." (PMID 25502799, 2014). "The IDH1 or IDH2 genes are mutated in 50%–80% of astrocytomas, oligodendrogliomas or oligoastrocytomas of grades II and III, and secondary glioblastomas." (PMID 24202337, 2013). "It has been demonstrated that mutations of the IDH1 and IDH2 gene (IDH1R132, IDH2R172) in glioblastomas are associated with the production of the TET inhibiting oncometabolite 2-hydroxyglutarate." (PMID 24386123, 2013). "The Arg172 and Arg140 mutants of IDH2 and glioblastoma SF188 cells under hypoxia convert 2OG to d-2-hydroxy-glutarate in this “reverse-reaction” mode." (PMID 22675360, 2012). "IDH1 or IDH2 mutations have been identified in more than 70% of CNS neoplasms diagnosed as grade II and III astrocytoma, oligodendroglioma, oligoastrocytoma, and secondary glioblastoma." (PMID 40546613, 2025). "This attribute gains importance given that, amongst WHO Grade 2/3 astrocytomas, oligodendrogliomas, and glioblastomas developing from these lower grade entities, IDH1 mutation occurs at codon number 132 in over two-thirds of these, with IDH2 mutations occurring in 6% of them." (PMID 36831683, 2023). "IDH2 (R172K) mutation rate in LGG was 3.99% and in glioblastoma was 0.25%." (PMID 35982398, 2022).
glioblastoma (continued). "Isocitrate dehydrogenase 1 (IDH1) and IDH2 mutations are favorable prognostic factors and can facilitate diagnosing astrocytomas and oligodendrogliomas, whereas IDH-wildtype is associated with lower overall survival and characterizes glioblastomas." (PMID 36291914, 2022). "Mutations in IDH1 or its homolog 2 (IDH2) have been identified as early molecular events in the development of astrocytomas and oligodendrogliomas, and they occur in various types of malignancies, including IDH-mutant glioblastoma (grade IV)." (PMID 31968687, 2020). "If current recommendations for the adult setting were to be applied, the presence of TERT promoter mutation in combination with an absence of IDH1/IDH2 mutation would be compatible with a diagnosis of diffuse astrocytic glioma, with molecular features of glioblastoma, WHO grade IV." (PMID 32493417, 2020). "No case of glioblastoma was detected with IDH2 gene mutation." (PMID 28785587, 2017). "A seismic shift in glioblastoma classification occurred based on the molecular biomarkers IDH1 (isocitrate dehydrogenase 1) and IDH2 (isocitrate dehydrogenase 2)." (PMID 40564017, 2025). "Promoter meythlation of the O6-methylguanine-DNA methyltransferase (MGMT) and IDH1/IDH2 has a particularly high prevalence in LGG, and methylation of the MGMT promoter is predictive for treatment response in glioblastoma patients." (PMID 34277415, 2021). "At the molecular level, 90% of glioblastomas harbor wildtype isocitrate dehydrogenase 1 and 2 genes (IDH1 and IDH2) distinguishing them from the remaining 10%, the so-called secondary glioblastomas, with a better prognosis." (PMID 33435218, 2021). "BCAT1 expression in glioblastoma tumors is specific to those carrying wild-type isocitrate dehydrogenase 1 and 2 (IDH1 and IDH2)." (PMID 29211698, 2018). "A study has shown that the siRNA knockdown of either IDH1 or IDH2 can significantly reduce the proliferative capacity of a glioblastoma cell line expressing both wild-type IDH1 and IDH2." (PMID 29661250, 2018). "Glioblastoma (GBM) is the most aggressive form of adult-type diffuse glioma and is characterized by the absence of IDH1 and IDH2 mutations." (PMID 40016450, 2025). "Considering glioblastoma is specifically defined as having wild-type IDH1, the upregulation of IDH1 but not IDH2 in this study is likely due to increased mutant IDH2 expression over wild-type IDH2 normally seen in the presence of wild-type IDH1." (PMID 41034696, 2025). "Our data are in line with previous research demonstrating overexpression of wild-type IDH1, but not IDH2, in glioblastoma." (PMID 41034696, 2025). "Primary glioblastomas (originating de novo) are wild type for IDH1 and IDH2." (PMID 27586084, 2016). "Among the 13 patients with primary glioblastoma, none had an isocitrate dehydrogenase IDH1 or IDH2 mutation, and 3 patients (3/13; 23 %) showed radiographic responses or SD ≥6 cycles." (PMID 25529192, 2015). "Although mutations in these genes have been reported in other cancer types such as glioblastoma and mesothelioma, BAP1, IDH1 and IDH2 have not been previously linked to HCC." (PMID 25159915, 2014). "Glioblastoma is histologically defined as an infiltrating astrocytic glioma with microvascular proliferation or necrosis characterized by a lack of mutations in IDH1, IDH2, and histone H3 genes." (PMID 36831383, 2023). "IDH2-132H staining did not reveal evidence of mutant IDH1/2 expression, supporting a diagnosis of IDH-wild-type glioblastoma." (PMID 40282990, 2025).
glioblastoma (continued). "Among 50 glioblastoma samples, only 6 were detected mutant for isocitrate dehydrogenase 1 (IDH1), p.R132H and none for isocitrate dehydrogenase 2 (IDH2) and histone H3-3A." (PMID 35303162, 2022). "Several mutations in TCA Cycle enzymes and enzymes in adjacent metabolic pathways are commonly found in glioblastomas, and none more prevalently than isocitrate dehydrogenase 1 (IDH1) and 2 (IDH2)." (PMID 34277624, 2021).
oligodendroglioma (102 papers, 2013 to 2026). A well-differentiated (WHO grade II), diffusely infiltrating neuroglial tumor, typically located in the cerebral hemispheres. "Oligodendroglioma is genetically defined by mutations in isocitrate dehydrogenase 1 or 2 (IDH1/IDH2) and 1p/19q codeletion." (PMID 41928812, 2026). "Under the 2021 WHO classification, oligodendroglioma is defined exclusively by the presence of an IDH1 or IDH2 mutation together with whole-arm 1p/19q codeletion." (PMID 41375081, 2025). "VORANIGO (vorasidenib) is an IDH1/IDH2 inhibitor approved by the FDA on 6 August 2024 for adult and pediatric patients 12 years and older with surgically intervened Grade 2 astrocytoma/oligodendroglioma harboring IDH1/IDH2 mutations." (PMID 41304751, 2025). "In the updated classification, oligodendrogliomas are defined by the presence of isocitrate dehydrogenase IDH1 or IDH2 mutations and 1p/19q co-deletion." (PMID 40143126, 2025). "It was approved by the FDA in August 2024 for patients aged 12 and over with grade 2 astrocytomas or oligodendrogliomas with IDH1 or IDH2 mutation post-surgery." (PMID 40862786, 2025). "One of these cases was described in context of enchondromatosis (with a germline mutation of IDH2 R172G), which classically predisposes to astrocytomas and oligodendrogliomas." (PMID 38581034, 2024). "Oligodendroglioma is molecularly defined by the presence of the isocitrate dehydrogenase 1 (IDH1) (most commonly IDH1 p.R132H) or IDH2 mutations and 1p/19q codeletion, frequently with an additional Telomerase Reverse Transcriptase (TERT) promoter mutation." (PMID 39061087, 2024). "Recently identified molecular markers, including the non-reciprocal translocation resulting in a 1p/19q codeletion, and mutations in the IDH1 or IDH2 gene, have significantly enhanced our understanding and characterization of oligodendrogliomas." (PMID 39061087, 2024). "The combined presence of an IDH1 or IDH2 mutation and a 1p/19q codeletion is a diagnostic criterion for oligodendroglioma, IDH mutant and 1p/19q codeleted." (PMID 34958131, 2022). "The discovery of mutations in the IDH1 and IDH2 genes in astrocytic and oligodendroglial tumours has led to a biomarker-driven classification, forming an integrated diagnosis composed of the histological appearance and the molecular profile." (PMID 35029738, 2022). "Mutations in IDH1 and IDH2 have been frequently observed in astrocytoma and oligodendroglioma patients." (PMID 36347915, 2022). "Studies utilising human oligodendroglioma cells have shown that the IDH1 R132 mutation leads to higher enzymatic activity than that brought about by IDH2 R172." (PMID 36042521, 2022). "Of particular interest herein are the chromosomes 1p and 19q, which are co-deleted in the oligodendrogliomas with concurrent IDH1/IDH2 mutations." (PMID 36360312, 2022). "Oligodendroglioma is genetically defined as a tumor harboring a IDH1/IDH2 mutation involving the co-deletion of chromosome arms 1p and 19q." (PMID 35267650, 2022). "Oligodendroglioma is genetically defined as a tumor confirmed to harbor either an IDH1 or IDH2 mutation along with co-deletion of chromosome arms 1p and 19q." (PMID 34675774, 2021). "IDH2 mutation was detected in <1% (83/14,726) of cancers, but were present in 13% (6/46) of anaplastic oligodendrogliomas, 9% (9/102) of oligodendrogliomas, and in 5% (2/39) of cutaneous squamous cell carcinomas." (PMID 35996504, 2021).